ERG (ETS transcription factor ERG)
Diseases named in the same sentence as ERG in open-access papers (continued):
Sharing a sentence is not in itself a finding about the gene and the disease.
cancer (continued). "A subset analysis revealed, that this association was purely driven by ERG negative cancers (p < 0.0001) while the mitochondrial content was unrelated to PSA recurrence in ERG positive cancers (p = 0.7598)." (PMID 24261794, 2013). "More recently, crosstalk of NF-κB with another transcription factor involved in certain types of cancer has been identified – that with the Ets family member ERG." (PMID 23915189, 2013). "Commonly found with a TMPRSS2:ERG fusion, the concurrent loss of PTEN contributes to a poor prognosis in cancer in the presence of an existing TMPRSS2:ERG fusion with an increased risk of recurrence." (PMID 24018887, 2013). "It is of note that the relationship between all analyzed deletions (PTEN, 3p13, 5q21, 6q15) and the mitochondria content tended to invert within ERG-positive cancers." (PMID 24261794, 2013). "Our results indicate that ERG-rearrangements possibly induce metabolic changes in cancer cells by activating major metabolic signaling molecules such as NPY." (PMID 23390522, 2013). "We next demonstrated the affectivity of EigFusion on real cancer data that harbour ERG rearrangement in around 50% of the samples." (PMID 22811706, 2012). "An extensive evaluation of whole mount prostates has shown a nearly 100% concordance of ERG positive PIN with ERG positive carcinoma." (PMID 22860005, 2012). "Several studies demonstrated cooperation between TMPRSS2/ERG and other defective pathways in cancer progression." (PMID 21747944, 2011). "ERG protein level was comparable with its previously reported expression level in cell lines and cancer samples." (PMID 21747944, 2011). "Further studies have shown a role for TMPRSS2/ERG fusion in tumorigenesis in terms of proliferation, invasion and cancer initiation and progression." (PMID 21747944, 2011). "Given that qRT-PCR with a different probe design clearly validated ERG overexpression in fusion-positive carcinomas (see corresponding Results section below), fusion status as determined by FISH was used for subsequent SAM analysis." (PMID 21814574, 2011). "Within the very few genes showing under-expression in ERG-negative carcinomas with an even more marked fold-decrease in ERG-positive lesions, RBMS2 (nucleic acid binding protein) displayed a massive fold-change reduction, which we set out to validate." (PMID 21814574, 2011). "The cancer-specific survival at 11 years for the rearranged ERG/ETV1 and normal PTEN group was 59.8% and for the rearranged ERG/ETV1 and PTEN loss group was 41.0%." (PMID 20104229, 2010). "Across all cases, ERG expression was significantly different between cancer and benign tissues (Mann-Whitney-U p = 0.029)." (PMID 20860828, 2010). "None of the other cortical cytoskeleton genes differed significantly with respect to its expression between ERG-high and ERG-low cancer tissues." (PMID 20860828, 2010). "By that definition in the present series 22 of 45 cancers overexpressed ERG, by up to two orders of magnitude." (PMID 20860828, 2010). "We reported that deletion of the intermediate region between TMPRSS2 and ERG combined with duplication of the TMPRSS2–ERG fusion sequences is predictive of poor cancer-specific survival, an observation supported by other studies." (PMID 20104229, 2010). "In this data set, ERG is overexpressed in tumors in which the cancer metastasized to distant lymph nodes." (PMID 19356222, 2009). "The cancers containing fusion of 5′-C15orf21 to 3′-ETV1 sequences included the previously reported case containing ERG and ETV1 rearrangements in distinct cancer foci of the same prostate." (PMID 18594527, 2008). "Finally, genome-scale CRISPR screening data from the Cancer Dependency Map revealed that ERG exhibits selective dependency in lymphoid malignancies, with B-ALL cell lines displaying the strongest and most consistent depletion phenotypes." (PMID 41509392, 2025).
cancer (continued). "Since TMPRSS2/ERG is present in more than 50% of prostate cancer tumors, its presence in urine may predict the presence of cancer." (PMID 40115018, 2025). "Upon ERG activation, BasalLum cells give rise to the highly proliferative intermediate state, which subsequently transitions to the larger population of Krt8+ luminal cells characteristic of ERG-positive human cancers." (PMID 38585869, 2024). "Unlike urine, abnormally elevated levels of ERG proteins contained in serum EV are associated with advanced PCa, risk of cancer, and recurrence." (PMID 40353136, 2024). "A low level of PSAP immunostaining was also associated with high androgen receptor levels in both ERG-negative (p < 0.0001) and ERG-positive cancers (p < 0.0001)." (PMID 37892063, 2023). "Top expressed cancer-implicated gene targets for each TF converged on notable genes involved in cell signaling (SMAD3, PTPRJ), BCL6 regulation (FBXO11, BCOR), and transcriptional regulation (RUNX1, ERG, CUX1)." (PMID 38116118, 2023). "In addition, the association with PSA recurrence was stronger in ERG-negative (p < 0.0001) than in ERG-positive cancers (p = 0.0012)." (PMID 37892063, 2023). "ERG expression is very common in PCa tumors and is a well characterized marker that bears paradoxal prognostic value when looking either at biochemical recurrence or at metastatic progression/cancer-related mortality." (PMID 35410344, 2022). "Six genes (PDXDC1, ATF7IP2, LIN7C JTB, TTL, DVL2), which regulate the ERG signal transduction pathways, were retained in 4 out of 9 LT patients, were significantly involved in transcriptional mis-regulation in cancer (multiple testing adjusted p-value = 0.025)." (PMID 35773268, 2022). "Therefore, based on the previous reports, in our study, we aimed to figure out the potential of six urinary-exosome-originated cancer-related RNAs (ERG, PSMA, ARA7, PCA3, CK19, and EpCAM) in being biomarkers for the detection and prognosis of PCa." (PMID 35402423, 2022). "In our study, high expression of both KRT15 and KRT19 in low-risk ERG fusion negative patients was associated with the enrichment of common cancer-associated gene signatures, especially KRAS." (PMID 36033462, 2022). "Interestingly, genes in these cancer-related pathways showed an overall positive correlation with ERG expression." (PMID 36579559, 2022). "However, this time, we focused more on the fusion of exon 1 of TMPRSS2 to exon 4/5 of ERG, which is the most abundantly found rearrangement in T:E fusion-positive cancer, as a way to solidly establish T:E fusion-positive cancer." (PMID 36579559, 2022). "Herein, we find that ICC/IDC cancer cell heterogeneity is most notably governed by individual patient gene expression as opposed to commonly altered oncogenic pathways, including prostate cancer drivers like ERG and PTEN." (PMID 36229464, 2022). "Interestingly, we found that the increase in GSTP1-positive cancers in Black men was greater in ERG-positive cases." (PMID 34191807, 2021). "The SPINK1‐positive cancer cases were reportedly associated with poorer outcomes among ERG‐negative cancer cases." (PMID 35475132, 2021). "However, there are additional disordered drivers that are altered via more complex genetic mechanisms in cancer, such as specific frameshift mutations (e.g., NOTCH1), chromosomal translocations (e.g., BCR, ERG) or copy number variations (e.g., p14ARF)." (PMID 33806614, 2021). "Based on these results, we posited that differential levels of androgen receptor (AR) signaling in SPOP-mutant vs. ERG-fused cancers might be at the root of the incompatibility between the driver events." (PMID 33531470, 2021). "In contrast, among the PZ cancer cases, ERG‐/SPINK1‐ cases showed the highest GG (P = .0119)." (PMID 35475132, 2021).
cancer (continued). "It is demonstrated that O'PROTACs of lymphoid enhancer‐binding factor 1 (LEF1) and ETS‐related gene (ERG), two highly cancer‐related transcription factors, successfully promote degradation of these proteins, impede their transcriptional activity, and inhibit cancer cell growth in vitro and in vivo." (PMID 34397171, 2021). "TFAP2D expression was unrelated to patient outcome in ERG-positive cancers (p = 0.9453)." (PMID 32143573, 2020). "Survivin loss was significantly more common in cancers carrying TMPRSS2:ERG fusions (61% survivin negative) than in ERG wild‐type cancers (32% survivin negative; P < .0001)." (PMID 31893572, 2020). "Given that hnRNPA1 was strongly associated with ERG-positive cancers itself, it was expected that hnRNPA1 was positively linked to all ERG-associated deletions and inversely linked to all deletions associated to ERG-negative cancers." (PMID 32417965, 2020). "Furthermore, a large number of studies have shown that ERG is not only an oncogene that is related to a variety of cancers, it also participates in the embryonic developmental processes, including bone development, of a variety of organisms." (PMID 33633772, 2020). "First, compensatory SFRP4 upregulation might also appear in aggressive cancers with activated Wnt signaling due to reasons other than ERG fusion." (PMID 32677026, 2020). "As most chromosomal deletions are either linked to ERG positive or negative cancer, it was expected that several deletions are statistically linked to the CD138 expression which is also ERG related." (PMID 33195694, 2020). "Deletions of 3p13, 8p21, 10q23 (PTEN), 12q24, 16q24, and 17p13 are linked to ERG positive cancers and 5q21, 6q15, 13q14, and 18q21 to ERG negative cancers." (PMID 32488048, 2020). "This analysis revealed several significant associations in the combined analysis of all cancers but also in the subsets of ERG‐positive and ERG‐negative cancers." (PMID 31893572, 2020). "Subset analysis revealed that all these associations were again driven by the subgroup of ERG negative cancers but were largely absent in ERG-positive cancers." (PMID 32677026, 2020). "Regulation of ERG by miRNA-200b-3p in other cancers is a subject for future investigation." (PMID 32591615, 2020). "In ERG-positive cancers, a statistically significant difference was found for 5 of 11 deletions." (PMID 32377272, 2020). "Subset analyses showed that this association was solely driven by the subset of ERG-negative cancers (p < 0.0001) while outcome differences were not seen in ERG-positive cancers (p = 0.1917)." (PMID 32417965, 2020). "Subset analyses revealed that all these associations were strongly driven by the fraction of cancers lacking the TMPRSS2:ERG gene fusion." (PMID 32417965, 2020). "This held also true in the subset of ERG‐negative cancers (P < 0.0001), while this association was lost in ERG‐positive cancers (P = 0.0876)." (PMID 31736271, 2020). "LPD3 cancer samples exhibited seven commonly overexpressed genes, including ERG, GHR and HDAC1." (PMID 32203215, 2020). "In ERG-negative cancers these statistically significant associations were retained for ESRP1 in 8 and for ESRP2 in 9 chromosomal regions." (PMID 33339518, 2020). "Cancer-associated SPOP mutants show reduced binding, ubiquitination and degradation of oncoprotein substrates such as the androgen receptor and the ETS transcription factor ERG." (PMID 32365080, 2020). "It showed that most of these associations were driven by the subset of ERG-negative cancers but failed to reach statistical significance in ERG-positive cancers." (PMID 32417965, 2020). "However, a search for associations that do not depend on ERG must be carried out in separate subsets of cancers with ERG-positive and ERG-positive cancers." (PMID 32488048, 2020). "As aberrant ERG expression collaborates with Pten haplo-insufficiency to promote cancer progression, we assessed whether USP11 loss would affect ERG-dependent cellular processes." (PMID 30733438, 2019).
cancer (continued). "Subset analyses of ERG positive and ERG negative cancers revealed that these associations were stronger in ERG negative cancers (p< 0.0001 each)." (PMID 31452838, 2019). "High MAPT expression levels were also associated with a higher risk for biochemical recurrence in all cancers and in the subsets of ERG positive and ERG negative cancers (p < 0.0001 each)." (PMID 30823906, 2019). "These associations held also true in the subsets of ERG negative and ERG positive cancers, although not all p values remained significant probably due to the overall small numbers of MAPT positive cancers." (PMID 30823906, 2019). "PTPN12 immunostaining was more prevalent in ERG fusion positive than in ERG wild type cancers." (PMID 31606028, 2019). "That GSK3ß controls Wnt signaling by inactivation of ß-catenin both in the cytoplasm and in the nucleus might, thus, explain the predominance of nuclear GSK3ß in ERG positive cancers in our study." (PMID 30899444, 2019). "Future development of drug candidates inhibiting TOX–DNA interactions could follow previous studies where SMIs have been successfully developed via CADD to target the DNA-binding domains of other cancer drug targets, such as AR, ERG, and MYC." (PMID 31554191, 2019). "A subset analysis of revealed that this association was solely driven by cancers harboring TMPRSS2:ERG fusions (12.7% – 34.0%, p<0.0001) but was absent in fusion negative tumors (12.5% – 12.4%, p=0.4249)." (PMID 31557128, 2019). "We can only speculate why relevant associations between GSK3ß and genomic deletions were absented in ERG fusion positive cancers." (PMID 30899444, 2019). "Subset analysis of ERG fusion negative and positive cancers showed these associations in both subsets." (PMID 31043167, 2019). "In addition to its role as an oncogenic factor in PCa and other cancers, ERG is a key transcription factor in endothelial cells and regulates functions such as angiogenesis and cell survival, thus driving endothelial cell lineage." (PMID 30718921, 2019). "It showed that all associations were solely driven by the subset of ERG-negative cancers, while BAP1 staining was unrelated to the analyzed features in ERG-positive cancers." (PMID 31903168, 2019). "Within ERG fusion-negative cancers, ZIC2 expression was also strongly associated with 6q15 and 5q21 deletions (p < 0.001)." (PMID 31640781, 2019). "Finally, we examined the correlation of p16 cytoplasmic and nuclear staining in cancer cells with ERG expression in AA PCa." (PMID 31111520, 2019). "Also, the expression of ERG in cancer samples with TMPRSS2-ERG was significantly higher than in cancer samples without the fusion transcript (P < 0.001)." (PMID 31537872, 2019). "Although this association was found when all cancers were jointly analyzed (p < 0.0001), subset analysis revealed that it was largely driven by ERG-negative tumors." (PMID 29304771, 2018). "In addition, positive expression correlation of Ets-1 with pancEts-1 or ERG was observed in many types of cancers in public datasets derived from GEO." (PMID 29773901, 2018). "Among those mRNAs, the ERG level increased to the greatest extent in cancer tissues." (PMID 30291252, 2018). "In opposite some other biomarker were only prognostic in ERG-positive cancer." (PMID 29304771, 2018). "Secondly, advanced stage and severe conditions display strong epithelial staining, especially in ERG fusion-negative conditions - while ERG fusion-positive cancers lacked this association." (PMID 29725501, 2018). "Similarly, a statistically significant positive correlation was demonstrated between elevated ERG expression and the Gleason scores in cancer patients." (PMID 30042415, 2018). "However, the primary endpoints were the AUCs of the changes in PCA3 and T2:ERG biomarkers, and these endpoints were estimated with sufficient accuracy to conclude that the ability of biomarker change to predict cancer status was poor." (PMID 30300367, 2018).
cancer (continued). "Other biomarkers were only prognostic in ERG-positive cancers." (PMID 28146062, 2017). "eRG and pRG were further examined for enrichment of cancer-related pathways respectively." (PMID 28621677, 2017). "This analysis revealed that significant associations between GGH and adverse cancer clinical characteristics mainly existed in the subset of ERG negative cancers." (PMID 28146062, 2017). "Subgroup analysis of ERG-negative and ERG-positive cancers revealed that these associations were merely driven by the subset of ERG-negative cancers, while there was no unequivocal impact of GGH levels on the deletion status in ERG-positive cancers." (PMID 28146062, 2017). "A separate analysis of ERG negative and ERG positive cancers, however, revealed that in both subgroups strong associations were limited to FAM13C and deletions of PTEN (p < 0.0001)." (PMID 28415558, 2017). "Our data demonstrate, that the slightly higher rate of 8p deletions in ERG-positive (40.9%) than in ERG-negative cancers (34.7%) is entirely driven by its strong association with the ERG-linked PTEN deletion." (PMID 27880722, 2017). "In ERG negative cancers, FAM13C expression was also linked to deletions of 5q and 6q (p < 0.0001 each), although to a lesser extent as compared to PTEN deletions." (PMID 28415558, 2017). "Although future development of new VPC-18005 derivatives can be prioritized based on their selective binding towards ERG, those showing promiscuous or increased specificities for alternative ETS factors should be considered as lead therapeutics towards cancers linked to those factors." (PMID 28465491, 2017). "In univariate analysis, 18q deletions were strongly linked to biochemical (PSA) recurrence in all cancers (P < 0.0001) as well as in the subsets of 2,650 ERG-negative (P = 0.0002) and 2,732 ERG-positive cancers (P = 0.0019)." (PMID 27861151, 2016). "For example, in African American patients, ERG-negative status is found to be associated with high-grade cancers." (PMID 27191272, 2016). "Understanding the homeostatic function of ERG in endothelial cells will provide insight into novel approaches to promote vascular health, as well as possible therapeutic options to selectively target the oncogenic function of ERG in cancer." (PMID 27208692, 2016). "Interestingly, RNAi-mediated inhibition of ERG in VCaP cells abrogates aggressive cancer cell behavior." (PMID 27223260, 2016). "To evaluate the chronological development of TMPRSS2:ERG fusion and 6q15 deletions we searched for tumors with focal 6q15 deletions arising in homogeneously ERG-positive cancers and tumors with focal ERG positivity arising in homogeneously or heterogeneously 6q15 deleted cancers." (PMID 26684029, 2016). "Since chromothripsis is observed early in prostate tumorigenesis, and is present in 30% of insignificant GS6 cancers, we next examined, whether its incidence depends on ERG status." (PMID 26337081, 2015). "Alterations at ERG, PTEN and c-myc genes are frequently observed in PCa, and considered to drive disease progression None of these loci was affected by chromothripsis in insignificant GS6, large volume GS6 or GP3 associated with GP4 in GS7 cancer." (PMID 26337081, 2015). "Such a cooperative role fits well to our observation that SOX9 expression was linked to PTEN deletion at least in the subset of cancers lacking ERG fusion." (PMID 26030748, 2015). "For ERG, a total of 113 cases (11%) did not have evaluable staining data either because of core loss or because lack of cancer in the core samples." (PMID 26172920, 2015). "Absent or reduced SOX9 expression was strongly linked to biochemical (PSA) recurrence in the subset of ERG-positive cancers (p<0.0001), but not in ERG-negative cancers (p = 0.80)." (PMID 26030748, 2015). "Elevated VEGFR-1 expression was linked to high Gleason grade and advanced pT stage in TMPRSS2:ERG negative cancers (p = 0.0008 and p = 0.001), while these associations were absent in TMPRSS2:ERG positive cancers." (PMID 25894226, 2015).